ENSG00000202434
Synonyms: LOC124900524
Gene: Small nucleolar RNA gene on chromosome 2 (197,404,718 to 197,404,854, forward strand). Ensembl gene ENSG00000202434.
Gene Ontology:
Biological process: RNA processing
Cellular component: nucleolus
Homologues: Orthologues: rat LOC120100360 (73% identical), rat LOC120099067 (69% identical), rat LOC120095411 (64% identical), rat LOC120099453 (61% identical), mouse Gm24728 (61% identical), mouse Gm54692 (61% identical), rat LOC120102009 (50% identical). Paralogues in human: SNORA4 (85% identical).